SNORA31B (small nucleolar RNA, H/ACA box 31B)
Gene: Small nucleolar RNA gene on chromosome 13 (45,336,314 to 45,336,447, reverse strand). Ensembl gene ENSG00000253051.
Gene Ontology:
Biological process: RNA processing
Cellular component: nucleolus
Homologues: Orthologues: chimpanzee SNORA31B (99% identical), macaque SNORA31B (96% identical), rat LOC120102627 (75% identical). Paralogues in human: SNORA31 (69% identical).